CD14 (CD14 molecule)
Diseases named in the same sentence as CD14 in open-access papers (continued):
Sharing a sentence is not in itself a finding about the gene and the disease.
meningitis (3 papers, 2007 to 2024). A disorder characterized by acute inflammation of the meninges of the brain and/or spinal cord. "From our in vivo studies using single knockout mice, it appears that TLR2 and CD14 both are protective in meningitis, although by different mechanisms." (PMID 17428319, 2007). "Our treatment study compares the host response mediated by TLR2 and CD14 in meningitis, and illustrates the requirement and success of adjuvant therapy, under conditions of harmful inflammation in TLR2-deficient mice." (PMID 17428319, 2007). "Because both strains showed excessive TNF, we compared the treatment response in wt, TLR2-/-, CD14-/-, and CD14-/-/TLR2-/-double knockout mice with meningitis to antibiotic treatment and/or anti-inflammatory treatment with TACE inhibitor." (PMID 17428319, 2007).
myeloid leukemia (3 papers, 2011 to 2024). A clonal proliferation of myeloid cells and their precursors in the bone marrow, peripheral blood, and spleen. "In this study we demonstrated that lapatinib induced myeloid leukemia cell death in CML K562, MEG-01, AML HL-60 and NB4 cells and showed much more toxicity than their normal counterpart human CD14+ monocytes, or mouse bone marrow cells." (PMID 22216158, 2011).
Neonatal sepsis (3 papers, 2005 to 2019). Systemic inflammatory response to infection in newborn babies. "The biomarker soluble CD14 subtype (sCD14-ST) seems promising in the diagnostic process of neonatal sepsis." (PMID 31159729, 2019).
pancreatitis (3 papers, 2010 to 2021). Inflammation of the pancreas. "Among cell surface changes, the diminished expression of human leukocyte antigen class II (HLA-DR) on circulating CD14+ monocytes is a hallmark of altered immune status in patients after stressful insult (for example, trauma, severe surgery, hemorrhagic shock, pancreatitis, burn, and sepsis)." (PMID 20385017, 2010). "The most promising use of HLA-DR expression as a marker on CD14+ cells is its association with infection after non-infectious insults such as surgery, liver transplantation, trauma, pancreatitis, or burn injury." (PMID 20385017, 2010).
Peri-Implantitis (3 papers, 2024 to 2025). An inflammatory process with loss of supporting bone in the tissues surrounding functioning DENTAL IMPLANTS. "IL-1β +3954 C/T, ET-1 and IL-1β, MMP-8 rs11225395 (T allele), MMP8 (−799 C/T), and CD14 rs2569190 showed consistent associations with increased peri-implantitis risk, while the results for TNF-α −308 G/A were inconsistent across populations." (PMID 41373620, 2025). "The results indicated that smoking and the presence of the TNFα-308 GA/AA genotype significantly increased the risk of peri-implantitis, while the CD14-159 CT/TT polymorphism acted as a protective factor." (PMID 41373620, 2025). "Investigations on CD14 rs2569190, CXCR2, and miR-27a-3p rs895819 polymorphisms suggested possible associations with peri-implantitis risk." (PMID 41373620, 2025). "Nevertheless, consistent associations were observed for certain polymorphisms—particularly CD14 rs2569190, IL-1β +3954 C/T, and TNF-α −308 G/A—across independent populations, supporting a moderate level of confidence in these findings as potential biomarkers for peri-implantitis susceptibility." (PMID 41373620, 2025). "The aim was to evaluate the association between single-nucleotide polymorphisms (SNPs) in genes involved in inflammation and bone metabolism (BMP-4, BRINP3, CD14, FGF-3, FGF-10, GBP-1, IL-1α, IL-1β, IL-10, LTF, OPG, and RANKL) and peri-implantitis." (PMID 41373620, 2025). "The qualitative evidence indicates that certain polymorphisms—particularly in the CD14, TNFα, IL-1, and EGF genes—show consistent associations with increased susceptibility to peri-implantitis, while others (e.g., MMP13, TGFB3, RANKL) demonstrate no clear relationships." (PMID 41373620, 2025).
peritonitis (3 papers, 2014 to 2018). Inflammation of the peritoneum (tissue that lines the abdominal wall and covers most of the organs in the abdomen). "In addition to the CD14 rs2569190 polymorphism, we observed several factors that were related to death such as emergency surgery, APACHE-II score, peritonitis, and heart disease." (PMID 29426837, 2018). "Interestingly, in patients with acute bacterial peritonitis, the increase in CD14+ MØs was much greater than CD1c+ DCs, and the ratio of MØ to DC skewed up significantly in peritonitis samples." (PMID 28065517, 2017). "These distinctive kinetics of CD14+ MØs and CD1c+ DCs during the course of PD therapy, as well as peritonitis episodes, has implied a different recruitment or differentiation processes, driven by local cytokines/chemokines under steady state and during inflammation." (PMID 28065517, 2017). "In addition, Fn14 expression is increased in monocytes/macrophages (CD14+) present in peritoneal effluents from PD patients with peritonitis compared to patients without peritonitis." (PMID 24599047, 2014).
pertussis (3 papers, 2023 to 2024). A contagious bacterial respiratory infection caused by Bordetella pertussis. "Using a least absolute shrinkage and selection operator (lasso) regression model, cord blood (CB) plasma IL-2, IL-17A, IL-31, and soluble CD14 (sCD14) were positively associated with pertussis IgG levels at 12 months, while CB plasma concentrations of APRIL and IL-33 were negatively associated." (PMID 37251388, 2023). "In this study, five important human genes (KRT10, FGG, TLR4, CD14, and MD2) reported in the development and spread of pertussis and staphylococcus aureus infections." (PMID 37169818, 2023).
prion disease (3 papers, 2014 to 2020). A transmissible disease that is caused by a protein that is able to induce abnormal folding of normal cellular proteins, leading to characteristic spongiform brain changes, which are associated with neuronal loss without an inflammatory response. "Absence of Cd14 delays progression of prion diseases accompanied by increased microglial activation." (PMID 31959236, 2020).
schistosomiasis (3 papers, 2014 to 2023). An infectious disease caused by parasitic trematodes of the genus Schistosoma that colonize human blood vessels and release eggs that can cause granulomatous reactions leading to acute (swimmer's itch or acute schistosomiasis syndrome) or chronic disease. "Independent t-test was carried out to evaluate the association between CD14 genetic variants and S. haematobium egg count, age of participants and the packed cell volume (PCV) of individuals with schistosomiasis and malaria infection or schistosomiasis infection alone." (PMID 37684680, 2023). "In support of our findings, cellular therapy of monocytes (CD14+ CD11b+) contributes to tissue remodeling, reduces the production of TGF-β and upregulates Fizz1 (M2 marker) expression in the liver during experimental schistosomiasis." (PMID 36263057, 2022).
scrapie (3 papers, 2011 to 2020). A fatal disease of the nervous system in sheep and goats, characterized by pruritus, debility, and locomotor incoordination. "In the current study, none of the target genes (GFAP, SAA3, CXCL10, CD14, S100A9, and IL1B) associated with the acute phase response and inflammation were differentially expressed in the hippocampus of animals with and without scrapie." (PMID 31924264, 2020).
silicosis (3 papers, 2021 to 2023). Silicosis is a respiratory disease caused by breathing in (inhaling) silica dust. "The expression of PD-L1 on CD14+ monocytes in peripheral blood of patients with silicosis and asbestosis was significantly lower than that of healthy controls." (PMID 37275876, 2023). "The percentages of circulating PD-L1+ CD14+ monocytes were significantly decreased in the asbestosis (mean 0.541%) and silicosis (mean 0.544%) groups compared to the healthy control group (mean 1.203%, P < 0.01)." (PMID 34022844, 2021). "Similarly, lower percentages of circulating PD-L2+ CD14+ monocytes were observed in the asbestosis (mean 0.541%) and silicosis (mean 0.525%) groups than in the healthy controls (mean 1.161%, P < 0.01)." (PMID 34022844, 2021). "Similarly, significantly lower PD-L1 and PD-L2 expression was detected on CD14+ monocytes from patients with asbestosis and silicosis than on cells from healthy controls." (PMID 34022844, 2021). "The expression of PD-1 on CD4+ and CD8+ T cells and the expression of PD-L1 and PD-L2 on CD14+ monocytes in peripheral blood of silicosis patients are significantly lower than those of healthy people, and the downregulation of PD-1 may be related to the single nucleotide polymorphism of PDCD1 gene." (PMID 37275876, 2023).
thyroid cancer (3 papers, 2024 to 2025). "This study highlights HLA-DR+CD14+CD66b+ monocytes as a significant immune cell population within the TME of thyroid cancer, demonstrating their potential utility as a biomarker for distinguishing malignant from benign cases." (PMID 40731885, 2025).
acute graft versus host disease (2 papers, 2019 to 2020). A syndrome of immunologically mediated tissue damage that may occur following an allogeneic transplant, usually affecting the skin, liver, and GI tract. "In contrast, the frequency of CD14+HLA-DRlow/negM-MDSCs is significantly increased in the peripheral blood after allo-HSCT, especially in patients with acute graft-versus-host disease." (PMID 30885244, 2019).
acute lymphoblastic leukaemia (2 papers, 2011 to 2022). "This novel partner cell line is a tri-hybrid of IL-4 secreting Th2 lymphoblast derived from a patient with acute lymphoblastic leukaemia (T), CD20+ B lymphoblast, also derived from a patient with acute lymphoblastic leukaemia (W), and IL-6 secreting peripheral blood-derived CD14+ monocyte (M)." (PMID 22373339, 2011).
adenoma (2 papers, 2012 to 2022). A neoplasm arising from the epithelium. "More recently, researchers in the Visvader laboratory have shown that, in cells derived from PyMT adenomas (early-stage lesions), CD14 and c-kit, along with CD49f/CD24, enriches for cells with colony-forming potential." (PMID 22225988, 2012). "Interestingly, CD14 a co-receptor of TLR4 is downregulated in our study, contrary to TLR4 expression in adenoma." (PMID 35486660, 2022).
age-related macular degeneration (2 papers, 2014 to 2021). Age-related loss of vision in the central portion of the retina (macula), secondary to retinal degeneration. "Our previous study identified a hypomethylated IL17RC promoter and elevated expression of IL17RC on CD14+ monocytes in the peripheral blood of patients with age-related macular degeneration." (PMID 24885153, 2014). "Furthermore, immunochemical examination of human eye samples of age-related macular degeneration showed the presence of the leukocyte antigens CD45, CD4, CD8, CD14, and CD83 in the choroid." (PMID 34963463, 2021).
amebiasis (2 papers, 2019 to 2021). A parasitic infectious disorder caused by amoebas. "Interestingly, expression of TNF and CXCL1 was higher in monocytes from male individuals than in those from females; this applied to both Ly6Chi monocytes in the murine model of amebiasis and CXCL1 in LPS-stimulated CD14++CD16- monocytes from healthy human subjects." (PMID 33829283, 2021). "In addition, the up-regulated DEGs were significantly enriched in 12 pathways such as NF-kappa B signaling pathway including LYN, LY96, CCL4, CD14; ECM-receptor interaction pathway including CD44, COL6A3, COL1A2, FN1 and Amoebiasis pathway including COL1A2, ITGB2, CD14, FN1." (PMID 31355054, 2019).
ANCA-associated vasculitis (2 papers, 2020 to 2024). "Notably, elevated levels of CD14+ CD16+ have been observed in conditions such as inflammatory pain and ANCA-associated vasculitis, leading to their identification as inflammatory monocytes." (PMID 38389539, 2024).
aneurysm (2 papers, 2009 to 2013). Bulging or ballooning in an area of an artery secondary to arterial wall weakening. "Deletion of CD14 reduced the incidence of AAAs and TAAs induced by AngII infusion as well as aneurysm diameter and weight." (PMID 23537804, 2013). "Genes that can be considered as markers for the following cell types were upregulated in aneurysms: neutrophils (Csf3r); T lymphocytes (Cd3d) and B lymphocytes (Blnk, Cd72, various immunoglobulin genes); and monocyte/macrophages (Cd14, Cd68)." (PMID 19580648, 2009).
Ascites (2 papers, 2016 to 2021). Accumulation of fluid in the peritoneal cavity (between the layers of the peritoneum that lines the abdomen). "GM-CSF and CD45+CD14+ cells were both significantly enriched in non-miliary ascites compared to miliary." (PMID 27665539, 2016).
astrocytoma (2 papers, 2014 to 2021). "The monocyte differentiation antigen CD14, one of the proteins contributing to the over-representation of the MAPK pathway, has been reported to increase with grade in astrocytomas." (PMID 34641541, 2021).
autism (2 papers, 2016 to 2022). Persistent deficits in social interaction and communication and interaction as well as a markedly restricted repertoire of activity and interest as well as repetitive patterns of behavior. "Circulating CD14+ monocyte from children with autistic disorder (AD) and children diagnosed with perverse developmental disorder not otherwise specified (PDD-NOS) were found to differ in a number of activation pathways after gene enrichment analysis compared to typically developing children." (PMID 36688057, 2022).
autoimmune hepatitis (2 papers, 2018 to 2023). Hepatitis caused by autoantibodies. "An impaired gut-oral axis in autoimmune hepatitis could be also related to the increased level of Monocyte differentiation antigen CD14 we observed in PBCp with respect to HCs." (PMID 37569584, 2023). "Thus, pathologic inflammasome activation in CD14++ monocytes appears to be a common feature in at least two forms of autoimmune liver disease." (PMID 30072988, 2018).
autoimmune thyroid disease (2 papers, 2018 to 2023). Inflammatory disease of the thyroid gland due to autoimmune responses leading to lymphocytic infiltration of the gland. "Furthermore, CD14 + CD163 high monocyte DEGs were enriched in chemokine signaling pathways, antigen processing and presentation, autoimmune thyroid disease." (PMID 37041166, 2023).
autoimmune uveitis (2 papers, 2015 to 2021). An autoimmune form of uveitis (disease). "A previous study has demonstrated that glucocorticoid treatment is associated with an enrichment of CD14++CD16+cells in patients with autoimmune uveitis." (PMID 26658828, 2015).
babesiosis (2 papers, 2023 to 2025). Babesiosis refers to a condition caused by microscopic parasites that infect the red blood cells. "Our data also demonstrated an increased abundances of LBP and CD-14 in babesiosis, underlining the importance of the host inflammatory response and a possible modulating effect of LTF." (PMID 37353646, 2023).
bone sarcoma (2 papers, 2023). A sarcoma that arises from the bone. "Aggressive pediatric bone sarcomas exhibited an increased number of peripheral CD14+HLA-DRlow/neg immunosuppressive monocytes as well as an increase of cytotoxic T-Lymphocyte Associated protein 4 (CTLA4+) and CD14+ macrophage infiltrates." (PMID 37424864, 2023).
cardiac hypertrophy (2 papers, 2020 to 2022). "It has been shown that CD14 expression is increased in cardiac hypertrophy caused by TAC and further elevated after LPS stimulation." (PMID 33324685, 2020). "These contradictory results were clarified in the study by Han and colleagues who found that Ang II directly interacts with MD2 to facilitate the MD2/TLR4 complex formation, a process that is independent of LPS, it seems to explain why CD14 does not work in Ang II-induced cardiac hypertrophy." (PMID 33324685, 2020).
cardiomyopathy (2 papers, 2022 to 2024). A disease of the heart muscle or myocardium proper. "In the training dataset, the cardiomyopathy group's expression levels of CD14, CCL2, and SERPINA3 were significantly lower than the ones in the control group." (PMID 36148059, 2022). "In conclusion, with the intersection of multiple cardiomyopathy gene sets with different etiologies and WGCNA analysis and LASSO regression analysis, we screened out a key module (turquoise module) and three hub genes involved in cardiomyopathy progression (CD14, CCL2, and SERPINA3)." (PMID 36148059, 2022). "The hub genes (CD14, CCL2, and SERPINA3) can be used as markers to distinguish cardiomyopathy from non-cardiomyopathy individuals." (PMID 36148059, 2022).
chorioamnionitis (2 papers, 2020 to 2025). A morphologic finding indicating inflammation of the fetal sac membranes. "We performed targeted analyses utilising Random Forest Algorithm of the same eight cfRNA targets (IL1α, IL1β, IL6, IL8, IL10, IL18, CD14, TNFα) used in the chorioamnionitis study." (PMID 40464837, 2025). "Targeted analysis of IL1 A, IL1B, IL6, and CD14 in maternal plasma of the 2 d Sterile Chorioamnionitis Group animals did not improve predictive values with a mean AUC of 0.46 (95% CI 0.13–0.79), Sensitivity 67%, Specificity 57%, PPV 0.67, NPV 0.57." (PMID 40464837, 2025).
chronic myeloid leukemia (2 papers, 2018 to 2023). "Preliminary results suggest that the presence of BDCA1+CD14+ cells correlates with clinical features of acute and chronic myeloid leukemia." (PMID 30235890, 2018).
clear cell renal carcinoma (2 papers, 2023 to 2025). A malignant epithelial neoplasm of the kidney characterized by the presence of lipid-containing clear cells within a vascular network. "Here, we report that human clear cell renal carcinoma tumors stably express the lymphoid markers CD45, CD56, CD14, and CD16." (PMID 40440354, 2025).
Dengue hemorrhagic fever (2 papers, 2017 to 2021). A serious condition caused by Dengue virus infection. "Another example of SOCS1 suppression was observed in patient developing dengue hemorrhagic fever (DHF) and this suppression is associated with elevated levels of miR-150 in CD14+ monocytes infected with DENV2." (PMID 28555130, 2017).
dysplasia (2 papers, 2024). A usually neoplastic transformation of the cell, associated with altered architectural tissue patterns. "Together, increased proportions of CD14+ MDSCs and mostly CD15+CD16+ neutrophils were found to be associated with dysplasia." (PMID 38900571, 2024).
Encephalopathy (2 papers, 2011 to 2023). Encephalopathy is a term that means brain disease, damage, or malfunction. "In HIV patients with encephalopathy, perivascular macrophages in the brain were found to be CD14+CD16+." (PMID 21738687, 2011).
eosinophilia (2 papers, 2013 to 2021). "Studies have reported associations of irAEs with the recruitment of CD14+CD16+ monocytes, the presence of eosinophilia, increased neutrophil/lymphocyte ratio (NLR), as well as NK cell-mediated antibody-dependent cell-mediated cytotoxicity (ADCC) reactions." (PMID 34899357, 2021). "We found that eLPS did not suppress airway eosinophilia in MyD88- or IFN-γ ̃deficient mice while suppression was observed in mice deficient in CD14, TLR4 or TLR2 molecules." (PMID 23805294, 2013). "Addition of eLPS during Bt sensitization resulted in inhibition of airway eosinophilia in WT and also in CD14−/−, TLR4−/− and TLR2−/− mice, suggesting that these molecules are dispensable for the inhibition of airway eosinophilia induced by eLPS." (PMID 23805294, 2013).
esophageal cancer (2 papers, 2014 to 2017). A primary or metastatic malignant neoplasm involving the esophagus. "Circulating CD11b+CD14+HLA−DR− cells were found to be significantly increased in esophageal cancer and were associated with circulating IL-6 levels." (PMID 29326716, 2017). "PBMCs were isolated from esophageal cancer patients or healthy donors and were stained for detecting MDSCs using fluorochrome-labelled antibodies targeting CD14, CD11b, and HLA-DR." (PMID 25238263, 2014).